IGKV2D-19 (immunoglobulin kappa variable 2D-19 (pseudogene))
Synonyms: A12; IGKV2D19
Gene: Immunoglobulin variable (V) pseudogene on chromosome 2 (90,046,796 to 90,047,057, forward strand). Ensembl gene ENSG00000253765.
Diseases named in the same sentence as IGKV2D-19 in open-access papers:
IGKV2D-19 is named in the same sentence as 1 disease in open-access papers, as found by Europe PMC text mining. Sharing a sentence is not in itself a finding about the gene and the disease.
IGKV2D-19 shares sentences with these, for which no sentence is quoted: glioblastoma (1 paper).